CDK4 (cyclin dependent kinase 4)
Diseases named in the same sentence as CDK4 in open-access papers (continued):
Sharing a sentence is not in itself a finding about the gene and the disease.
breast tumors (continued). "In the multidisciplinary management of patients with HR+/HER2− advanced breast tumors with bone metastases, the integration of radiotherapy (RT) with CDK4/6 inhibitors remains a clinical challenge, with several aspects yet to be fully clarified." (PMID 40649034, 2025). "In patients with advanced HR+/HER2− breast tumors, these studies examined the efficacy of combination CDK4/6i with standard endocrine therapy (an aromatase inhibitor, letrozole, or an estrogen receptor antagonist, fulvestrant)." (PMID 38983782, 2024). "Produced in 2001, palbociclib became the initial CDK4/6-specific inhibitor to demonstrate activity versus a variety of human cancer cell lines and xenografts, including breast tumors." (PMID 38983782, 2024). "CDK4 and CDK6 (hereafter referred to as CDK4/6) have been shown to be essential in mediating breast tumor formation." (PMID 38831405, 2024). "Understanding how breast tumors develop these mechanisms is crucial, and overcoming CDK4/6i resistance is an urgent challenge." (PMID 36902831, 2023). "Given this, a series of selective oral CDK4/6 inhibitors, such as palbociclib, have been developed for the treatment of ER+ breast tumours." (PMID 36127291, 2023). "We previously reported that the CDK4 modification profile of breast tumors and cell lines can be predicted using the expression values of 11 genes." (PMID 37964967, 2023). "MALAT1 increased breast tumor cell proliferation by miR-124 sponging and activating the CDK4/E2F1 axis." (PMID 36597150, 2023). "In our previous studies in breast tumors and pleural mesotheliomas, we observed a variable presence of CDK4 T172-phosphorylation in most tumors." (PMID 37964967, 2023). "Do CDK4/6 inhibitors induce senescence in other proliferative cells within a breast tumor (e.g., fibroblasts, endothelium) and what is the impact of this?" (PMID 35248122, 2022). "Further work is needed to delineate the chromatin landscape of breast tumors resistant to PI3K or CDK4/6 inhibitors." (PMID 35774123, 2022). "In PubMed, The most frequently occurring words were human, cyclin-dependent kinase 4, female, animals, cyclin-dependent kinase 6, breast neoplasms, cell line, drug resistance, protein kinase inhibitors, and mice." (PMID 36530984, 2022). "ER+ breast tumors are targeted using selective estrogen receptor modulators (SERMs), aromatase inhibitors, cyclin-dependent kinases 4 and 6 (CDK4/6) inhibitors, and ER degraders also called selective estrogen receptor downregulators (SERDs)." (PMID 35392236, 2022). "One of the main factors of uncontrolled cell proliferation and CDK4/6 inhibitor resistance frequently seen in breast tumors is the deregulation of the cyclin D-CDK4/6-INK4-RB axis, upstream response, and downstream bypass mechanisms." (PMID 33597817, 2021). "Together, findings from our study supports the potential clinical use of anti-WEE1 therapy for ER+ breast tumors that have acquired resistance to endocrine therapy and are intrinsically resistant to CDK4/6 inhibitors." (PMID 34277427, 2021). "Breast tumors that progress on endocrine and CDK4/6 inhibitor therapies are often treated with combination of antiestrogens and mTOR inhibitors or with chemotherapies with nominal success." (PMID 34277427, 2021). "The MTA3 (Downregulated of MTA-3 in ER-negative Breast Tumors) pathway was associated (positively correlated) with two predicted IC50 vectors belong to L-685458(gamma-secretase) and PD-0332991(CDK4/6) drugs." (PMID 32174963, 2020). "Elacestrant, an oral SERD, inhibits ER signaling and growth of these CDK4/6i-resistant breast tumor cells." (PMID 31852484, 2019). "In breast tumor samples, the relative abundance of the T172‐phosphorylated form 3 of CDK4 was highly variable." (PMID 28566333, 2017). "In this study, we were also surprised by the high variability of the relative proportion of the T172‐phosphorylated form of CDK4 in breast tumors." (PMID 28566333, 2017).
breast tumors (continued). "In summary, we report that the presence and relative abundance of T172‐phosphorylated CDK4 varied among breast tumors and cell lines." (PMID 28566333, 2017). "Consistently, knocking down CDK4 in MDA or SUM159 cells also reduced the percentage of the BCSC CD44high/CD24neg subpopulation, suggesting CDK4 specifically maintains BCSC expansion in breast tumors." (PMID 27759034, 2016). "CDK4/6 inhibitors have shown favorable activity in combination with letrozole for treating patients with advanced ER+ breast tumors." (PMID 26460486, 2015). "Indeed, our data support the addition of RETi to CDK4/6i and/or endocrine therapy as a therapeutic strategy following resistance to combined CDK4/6i and endocrine therapy in ER+ breast tumors exhibiting RET overexpression." (PMID 39931212, 2024). "However, there is a very promising treatment for advanced breast tumors (hormone receptor-positive) with the drug CDK4/6, a cyclin-dependent kinase inhibitor that restores the immune response." (PMID 38500881, 2024). "In fact, breast tumors harboring ESR1 mutations have demonstrated greater sensitivity to selective estrogen receptor modulators such as tamoxifen and fulvestrant and to the combination of these endocrine therapies with CDK4/6, PI3K, or mTORC1 inhibitors." (PMID 38239650, 2023). "Furthermore, we showed that the CDK4 modification profile of breast tumors and cell lines can be predicted using the expression values of 11 genes." (PMID 37964967, 2023). "To support understanding of trials such as CAPItello-291 and gain insight into this emerging population of patients, we explored how CDK4/6 inhibitor treatment influences ER+ breast tumour cell function and response to fulvestrant and capivasertib after CDK4/6 inhibitor treatment." (PMID 37543694, 2023). "Indeed, GLS inhibition sensitizes breast tumours to CDK4/6 and PRAP inhibition and overcomes breast tumour resistance to mTOR inhibitors." (PMID 34572926, 2021). "In terms of mechanism, immune evasion may be associated with the abnormal expression of immune-related regulators, such as IFN-α and IFN-β, and change in tumor microenvironment of CDK4/6 inhibitor–resistant breast tumors." (PMID 33364954, 2020). "Our study suggests that the early identification of patients with a high ERα ENR of breast tumor cells, who may be resistant to ET, could lead to the inclusion of a CDK4/6 inhibitor or mTOR inhibitor in the treatment regimen." (PMID 31013810, 2019). "Therefore, we modified our 2D‐gel electrophoresis immunodetection assay to analyze the modified and native CDK4 forms in minimal amounts of frozen breast tumor samples extracted in urea buffer." (PMID 28566333, 2017). "As T172 phosphorylation is required for the opening of the catalytic cleft of CDK4 and its activity, these observations illustrate that engagement of breast tumor cells in the cell cycle can be dependent on or independent of CDK4 activity, as foreseen by previous cell cycle models." (PMID 28566333, 2017). "Preclinical studies using breast tumor cell lines, mouse models, and ex vivo patient tumor cells have demonstrated the efficacy of inhibiting CDK4/6 by PD0332991 (palbociclib) to arrest proliferation." (PMID 28566333, 2017). "As high grade breast tumors are enriched in BCSCs23, these results further suggest that CDK4 may regulate BCSC expansion." (PMID 27759034, 2016). "In our study, we assessed CDK4 gene expression in relation to the three grades of breast tumors." (PMID 27759034, 2016). "We speculated that lower proliferation rates in ER+/HER2- breast tumors with high levels of RelA may be due to diminished CDK4 levels." (PMID 26460486, 2015). "Also, the recently approved CDK4/6 inhibitor palbociclib had the same level of activity in breast tumors harboring altered and normal CDK4/6." (PMID 26474971, 2015).
breast tumors (continued). "In addition to directly affecting proliferation, alterations in cdk6 or cdk4 levels in breast tumor cells also differentially influence levels of numerous steroid metabolic enzymes (SMEs), including those involved in estrogen metabolism." (PMID 24848372, 2014). "The effect of stable cdk4 overexpression in breast tumor cells was therefore examined." (PMID 24848372, 2014). "We speculate that inhibiting Cdk4 in Her2+ breast tumors can suppress some malignant characteristics of tumor cells such as CA and the active generation of aneuploidy." (PMID 23776583, 2013). "The oncoprotein is overexpressed in approximately 30% of breast tumors, and hyper-activates and deregulates its downstream signaling networks, including the G1/S cell cycle phase via high levels of cyclin D and active cyclin D/Cdk4/6 complexes." (PMID 23776583, 2013). "In our model, cyclin D1amplification or p16 lost in breast tumors could be equivalent in maintaining CDK4 activity and therefore inactivating pRb checkpoint." (PMID 20174572, 2010). "Abrogation of Rb pathway function is frequent in breast tumors by loss of expression of Rb or altered expression of inhibitors of Rb activity (e.g. loss/silencing of CDKN2A (p16) and amplification and/or over expression of CCND1, CDK4, CDK6)." (PMID 16620391, 2006). "Serial single-cell RNA sequencing of estrogen receptor-positive (ER + ) breast tumors from multiple patient cohorts, combined with experimental analyses, uncovers molecular mechanisms of compensatory growth signaling that drive proliferation in endocrine +/- CDK4/6 inhibitor-resistant cancer cells." (PMID 40341770, 2025). "Serial single-cell RNA sequencing of estrogen receptor-positive (ER + ) breast tumors from multiple patient cohorts, combined with experimental analyses, uncovers molecular mechanisms of compensatory growth signaling that drives proliferation in endocrine +/- CDK4/6 inhibitor-resistant cancer cells." (PMID 40341770, 2025). "However novel treatments like CDK4/6 inhibitors have shown importance and antibody drug conjugates may be instrumental considering newer categories of Her 2 Low breast tumors." (PMID 38001750, 2023). "On the other side, to the best of our knowledge, there is no prognostic value reported in CTCs for CDK4 but Gulappa and colleagues suggested that the modulation of CDK4 expression could be an attractive target in the treatment of CRPC such as happens in breast tumours." (PMID 33635497, 2021). "While CDK4/6 inhibitors like Palbociclib in combination with TAM may potentially arrest the in vivo growth of ERmut expressing breast tumors, CDK2 inhibitors like Dinaciclib when given in combination with TAM may be more effective by inducing regressions in established ERmut expressing tumors." (PMID 29137354, 2017). "CDK4 may be the prominent driver of proliferation in the ER+/HER2- subtype of breast tumors." (PMID 26460486, 2015). "The advent of CDK4/6 inhibitors, namely, palbociclib, ribociclib and abemaciclib, has changed the management of oestrogen receptor (ER)-positive/HER2-negative advanced breast tumours." (PMID 41388212, 2025). "During the last years, CDK4/6 inhibitors have changed the treatment landscape of hormone receptor‐positive and HER‐2‐negative breast tumors offering large progression‐free intervals to many patients with invasive breast cancer." (PMID 39021492, 2024). "LINC01089 inhibited breast tumor cell proliferation and invasion, while induced cell apoptosis and G0/G1 arrest by CCND1, CDK4, and CDK6 down regulations." (PMID 36597150, 2023). "Therefore, we first tested whether the tool based on the genes selected for the CDK4 profile prediction in breast tumors and the corresponding RNA-seq breast references could correctly predict the profiles of thyroid tumors, using raw CP20M gene expression values." (PMID 37964967, 2023).
breast tumors (continued). "Our observation that phosphorylated CDK4 is the major modified form of CDK4 in a subgroup of basal‐like tumors and most HER2‐positive breast tumors provides objective arguments for extending the use of CDK4 inhibitors to these ER‐negative tumors." (PMID 28566333, 2017). "Analysis of The Cancer Genome Atlas's (TCGA) ER+ breast tumour cohort revealed alterations in the CDK4/CDK6/cyclin D pathway in about 35% of the patients, making them an ideal population for targeting CDK4 and CDK6." (PMID 28653662, 2017). "An additional study revealed that a triple combination of neratinib plus a CDK4/6 inhibitor plus endocrine therapy was more efficient in reducing proliferation and colony formation in HR-positive/HER2-low breast tumor cells (ZR-75-1) than CDK4/6 inhibitor plus endocrine therapy alone." (PMID 41301038, 2025). "Ribociclib functions as a cyclin-dependent kinase 4/6 inhibitor for first-line therapy against HR+/HER2‒ advanced breast tumors, and its bioavailability is not influenced by gastric pH alterations or food intake." (PMID 38425243, 2024). "Our results extend our demonstration in breast tumors and for pleural mesotheliomas: CDK4 phosphorylation was absent or very weak in normal quiescent thyroid tissue, but detectable in most thyroid tumors and derived cell lines." (PMID 37964967, 2023). "However, the CDK4/6 inhibitor Palbociclib, similar to that of BET inhibitor, achieved a synergistic effect with AKTi in suppressing breast tumor cell growth, suggesting that the kinase activity of CDK6 is important for the intrinsic resistance to AKTi." (PMID 30518851, 2018). "Here we demonstrate CDK4/6 inhibition blocks breast tumour metastasis without affecting tumour growth." (PMID 28067227, 2017). "As expected, we found that CDK4 is overexpressed in primary breast tumors compared with normal tissues." (PMID 27759034, 2016). "Our results from mechanistic studies in HMEC, gene expression analysis of ER+/HER2- tumors from the TCGA cohort and analysis of ER+/HER2- breast tumors by IHC implicate basal activity of RelA in suppressing proliferation through upregulation of IRF1 and downregulation of CDK4." (PMID 26460486, 2015). "Overexpression of cdk6 in breast tumor cells in culture has been shown to suppress proliferation, unlike the growth stimulating effects of its close homolog, cdk4." (PMID 24848372, 2014). "Overall, our data suggested that CDK4/6 inhibitors are unlikely to be useful in the treatment of MYC-dependent breast tumours." (PMID 24444383, 2014). "As the authors of both studies study point out, inhibition of CDK2 is of paramount importance for the induction of cell cycle arrest in breast tumor cells that respond to CDK4/6 inhibitors and without CDK2 inhibition, patients will undoubtedly develop resistance to this class of therapeutics." (PMID 36051751, 2022). "It is likely that c-myc-overexpressing breast tumors might not be sensitive to the CDK4/6 inhibition but may be more responsive to the CDK1/2 inhibitors." (PMID 32934206, 2020). "We show that CDK4 expression is elevated in the most aggressive TNBC subtypes and strongly associated with the basal-like subtype, ER negative and higher grade of primary breast tumors, all of which represent poor prognostic features of TNBCs." (PMID 27759034, 2016). "CDK4 levels in ER+/HER2- breast tumors may similarly be negatively regulated by RelA." (PMID 26460486, 2015). "In contrast to breast tumors, high CDKN2A expression measured by RNA-seq analysis in thyroid tumors, did not entirely correlate with elevated p16 expression and lack of CDK4 phosphorylation." (PMID 37964967, 2023).
non-small cell lung carcinoma (75 papers, 2013 to 2025). A group of at least three distinct histological types of lung cancer, including non-small cell squamous cell carcinoma, adenocarcinoma, and large cell carcinoma. "Of note, CDK4 inhibition was shown to be synthetically lethal with KRAS mutations in non-small cell lung cancer (NSCLC), an observation yet to be explored for PDAC." (PMID 30340359, 2018). "In EGFR mutant non-small-cell lung cancer, the CDK4/6 inhibitor Palbociclib can reverse the resistance to the EGFR inhibitor Osimertinib." (PMID 40563591, 2025). "Increasing evidence suggests that CDK4/6 inhibitors hold significant promise in the treatment of other cancers such as non-small cell lung cancer, esophageal cancer, and pancreatic ductal adenocarcinoma." (PMID 40307228, 2025). "After evaluating YTHDF1’s role in advancing tumor cell cycle progression, we examined its known targets, CDK2 and CDK4, in non-small cell lung cancer using RNA Binding Protein Immunoprecipitation Assay (RIP)." (PMID 40251202, 2025). "A study found that MEK inhibitor in combination with CDK4/6 inhibitor has significant anti-KRAS-mutant NSCLC (Non-Small Cell Lung Cancer) activity and radiosensitizing effect in preclinical models." (PMID 38600093, 2024). "DF1, as an oncogene, has been reported to increase G0/G1 cells by regulating CDK2, CDK4, and cyclin D1 translational efficiency in non-small cell lung cancer (NSCLC)." (PMID 35351856, 2022). "This is because palbociclib, a CDK4/6 inhibitor, showed an anti-tumor effect in patients with non-small cell lung cancer and CDKN2A alterations." (PMID 36119486, 2022). "The upregulation of piR-651, an oncogene, has been described as promoting tumour growth owing to mediation by Cyclin D1 and CDK4 (Cyclin Dependent Kinase 4) in non-small cell lung cancer." (PMID 36555927, 2022). "Unfortunately, CDK4/6is are found to have limited clinical activity as single agents in non-small cell lung cancer." (PMID 34138895, 2021). "Potential targeted therapies, such as anti-PD-1 antibodies and CDK4/6 inhibitors, have been reported for treating SMARCA4-deficient non-small cell lung cancer (SMARCA4-deficient NSCLC)." (PMID 33836796, 2021). "A recently conducted study in non-small cell lung cancer pointed out that downregulation of RCC1 can increase the sensitivity of immunotherapy by upregulating PD-L1 through the p27kip1/CDK4 axis." (PMID 34298996, 2021). "In a mouse non-small-cell lung-cancer model, the inhibition of CDK4/6, the downstream target of p16, resulted in increased CD4 and CD8 T cell infiltration in the tumor." (PMID 34948172, 2021). "To address this problem and to identify effective CDK4/6i combinations, we screened a library of targeted agents for efficacy in four non-small cell lung cancer lines treated with CDK4/6 inhibitors Palbociclib or Abemaciclib." (PMID 34138895, 2021). "Theoretically, small molecule CDK4/6 inhibitors (CDK4/6is) represent a logical therapeutic option in non-small cell lung cancers since most of these malignancies have wildtype RB, the key target of CDKs and master regulator of the cell cycle." (PMID 34138895, 2021). "When used as monotherapy, CDK4/6 inhibitors exhibit certain efficacy in solid tumors, such as non-small cell lung cancer (NSCLC) and mature teratoma." (PMID 32933570, 2020). "Other functional experiments have demonstrated that piR-651 promotes tumor formation in non-small cell lung cancer mediated by Cyclin D1 and CDK4." (PMID 32357464, 2020). "Aberrant activation of CDK4/6 kinase is the most common somatic event in non-small cell lung cancer (NSCLC)." (PMID 30647837, 2018). "Expression of CDH18 was lower in LS8107 and LS8313 cells and in the non-small cell lung cancer cell line H358, all of which fail to senesce following CDK4/6 inhibition." (PMID 29789718, 2018). "Notably, glycyrrhetinic acid has also been shown to induce G1-phase cell cycle arrest in human non-small-cell lung cancer cells by downregulating CDK4/6, CYCLIN D, and pRB." (PMID 39727652, 2024).